MTOR (mechanistic target of rapamycin kinase)
Diseases named in the same sentence as MTOR in open-access papers (continued):
Sharing a sentence is not in itself a finding about the gene and the disease.
tumor (continued). "We observed that the expression of phosphorylated AKT, mTOR and p70S6K decreased in Salmonella-infected tumor cells comparing to control groups." (PMID 26517244, 2016). "We have previously reported that the tumor-promoting function of lal−/− MDSCs is mediated, at least in part, through enhanced activation of the mTOR pathway, and that the mTOR pathway is involved in the differentiation of Lin− cells into Ly6G+CD11b+ cells." (PMID 26625314, 2016). "Tumor suppression by PTEN depends on its negative regulation of the phosphatidylinositol 3-kinase-Akt-mammalian target of rapamycin (PI3K-Akt-mTOR) signaling pathway." (PMID 27506936, 2016). "mTOR inhibitor used alone exerts a promising anti-tumor activity, which is enhenced by combining with other drugs for OS." (PMID 27177330, 2016). "This reduced the activation of mTOR in lung tissue which corresponded to a 72% reduction in tumor burden." (PMID 27004404, 2016). "Treatment of tumor cells or xenografts with PI3K/AKT/mTOR pathway inhibitors abrogated the increased P-AKT expression and enhanced antitumor activity of C1A at well-tolerated doses." (PMID 27362804, 2016). "There is also evidence that the LDH-B isozyme also participates in tumor development and is regulated by oncogenic transcription factors mammalian target of rapamycin (mTOR) and signal transducer and activator of transcription 3 (STAT3)." (PMID 27242914, 2016). "Autophagy is inhibited by the mTOR signaling and generally activated by conditions of nutrient deprivation, oxidation, infection and tumor suppression." (PMID 27769241, 2016). "We collected tissue at 3 and 7 days after transgene activation to examine cytokine/Stat3 and mTOR/S6 signaling during tumor initiation and early expansion." (PMID 26859571, 2016). "In conclusion, our meta-analysis demonstrated that the positive expression of mTOR and p-mTOR was significantly correlated with the unfavorable outcomes on the depth of tumor invasion, TNM stage, differentiation degree and LNM." (PMID 27835987, 2016). "Two phase I trials combining temozolomide with mTOR inhibitors and concurrent radiotherapy have been conducted, showing the treatment to be well tolerated with decreases in tumor metabolism noted on PETCT-based imaging." (PMID 27043632, 2016). "The use of these compounds has been applied to CRC treatment, in order to selectively inhibit tumor-associated activity of kinases such as EGFR, VEGFR, PDGFR, PI3K and mTOR." (PMID 27286453, 2016). "In this study, we show that the hypoxic microenvironment of a tumor is resistant to mTOR inhibitors, and we propose that targeting the hypoxic region of a tumor is an effective approach to enhance their anti-tumor efficacy." (PMID 27153561, 2016). "A study showed combined treatment of crizotinib and an mTOR inhibitor led to reduced tumor growth and prolonged survival in ALK F1174L/MYCN-positive models compared to single agent treatment." (PMID 26786851, 2016). "Recent studies have shown activation of autophagy as one of the critical molecular alterations that limits the anti-tumor effects of PI3K/mTOR inhibitors." (PMID 27823983, 2016). "The PI3K/AKT/mTOR pathways are activated by receptor tyrosine kinases (RTK) that transmit extracellular signals from the tumor microenvironment." (PMID 26952093, 2016). "During tumor expansion, mTOR/S6 signaling persisted in GLI2A+ tumor cells and was also detected in GLI2A-negative epithelial cells, suggesting activation via a paracrine mechanism in the latter cell population." (PMID 26859571, 2016). "al. showed that PD-1 inhibition boosts T cell anti-tumor responses by restoring mTOR activity and glucose flux in tumor-reactive T cells." (PMID 26885366, 2016). "The correlation between tumor grading and activation of p-mTOR in NETs is controversial probably because NETs are rare tumors but also because the poor differentiated NETs are underrepresented in the most of studies." (PMID 26934559, 2016).
tumor (continued). "Inhibition of mTOR improved survival and induced tumor shrinkage downstream of mTOR via S6 leading to regression of tumors into benign, relatively non-proliferative cysts." (PMID 27200288, 2016). "Accumulating evidences have demonstrated that mTOR and its downstream effectors such as p70S6K and 4EBP1 have central roles not only in cell growth but also in tumor invasion and metastasis." (PMID 27595116, 2016). "There is however evidence of crosstalk between the mTOR-conducted signaling and other signaling pathways which will allow tumor cells to escape mTOR-inhibitory therapy." (PMID 27461218, 2016). "The PI3K–Akt–mTOR signaling pathway plays an important role in controlling proliferation and survival of tumor cells in various types of malignancy, including DLBCL." (PMID 27835906, 2016). "This decrease in mTOR/SK1 signaling correlated with significant (~twofold) tumor size reduction in the combination group in comparison to the single treatment groups." (PMID 27821815, 2016). "In particular, the action of PD-L1 directly on tumours reduces glycolysis by impinging on mTOR activation and on the expression of glycolytic enzymes, this being sufficient to restore T cell activity." (PMID 27083002, 2016). "Based on the results of our study, we inferred that PDK1 protected BCL-2, BCL-xL, and PI3K/Akt/mTOR from degradation and that the persistent stabilization of these proteins made the tumor cells resistant to apoptosis, thus conferring survival advantages." (PMID 26593251, 2016). "mTOR's critical function in cell cycle progression was thereafter extended to several tumour cell types." (PMID 27863419, 2016). "The mTOR inhibitors have strong anti-tumor effects compared with CNI-mediated immunosuppression in mouse models and in renal or heart transplant recipients." (PMID 27171501, 2016). "Target: mammalian target of rapamycin (mTOR) inhibitorMechanism of action:Binds to FKBP-12, and the protein-drug complex inhibits mTOR.Inhibition of mTOR activity results in a G1 growth arrest in treated tumor cells." (PMID 27119356, 2016). "We found that the inhibition of autophagy by A-SMase determines tumour response to cisplatin in a mechanism involving activation of the Akt/mammalian target of rapamycin (mTOR) pathway." (PMID 27107419, 2016). "Various novel agents are being evaluated for the treatment of patients with NET, including second generation mTOR inhibitors that use a multitargeted inhibition approach with the potential to overcome tumor escape mechanisms." (PMID 27539383, 2016). "In RCC, galetin-1 can activate HIF-1α-mTOR signaling axis, enhance the migration ability of tumor cells, and promote tumor progression." (PMID 27259255, 2016). "Activation of mTOR leads to increased tumour progression and expression of pro-angiogenic growth factors by two distinct complexes: mTOR complex 1 (mTORC1) and mTOR complex 2 (mTORC2)." (PMID 27206490, 2016). "As mammalian target of rapamycin (mTOR) is a critical regulator of aberrant energy homeostasis, it is an attractive target for anti-tumor intervention." (PMID 27056897, 2016). "API-2 (triciribidine) and everolimus (RAD-001), two inhibitors that target the PI3K/AKT/mTOR pathway, showed enhanced inhibition of cell viability and proliferation in B7-H3 knockdown tumor cells compared to their B7-H3 expressing counterparts." (PMID 26771843, 2016). "Aberrant regulation of the PI3K/Akt/mTOR axis often confers a proliferative advantage to tumor cells and contributes to the development of drug-resistance mechanisms." (PMID 27494886, 2016). "Interaction between eukaryotic translation initiation factor 4E-binding protein (4E-BP1) and MCV small T antigen is thought to up-regulate mTOR pathway in MCV-positive tumor." (PMID 26536665, 2016).
tumor (continued). "AKT phosphorylation plays an important role in tumor survival and development, and the Akt/mTOR signaling pathway is a classical autophagy pathway." (PMID 27275542, 2016). "The inhibitory activity of RER is apparently mediated by the inhibition of TGF-β-induced tumor cell proliferation supported by AKT/mTOR pathway and tumor cell invasion." (PMID 27863384, 2016). "In the present study, there was a significant increase in phosphorylation as well as the total amount of mTOR in skeletal muscles of tumor-bearing mice." (PMID 27462398, 2016). "Overall, these results support a mechanism of tumor cell death by 40 μM of FF + 2 mM of 2-DG involving attenuation of the UPR by mTOR adding to the burden of both energy and ER stress induced by this combination of drugs." (PMID 27183907, 2016). "In the present review we discuss the role of macrophages in the tumor microenvironment and the role of mTOR pathway in M1 and M2 differentiation." (PMID 28074082, 2016). "Meanwhile, transfection of cells with constitutively active Akt1 greatly blocked the inhibitory effect of ATR-1 as well as the up-regulation of Bax and Bad, thereby proving that the anti-tumor effect of ATR-1 relies on the inhibition of PI3K/Akt/mTOR pathway." (PMID 26931119, 2016). "Genetic alterations in the PI3K/AKT/mTOR pathway were detected in 36 % of the 51 SCLC tumor samples." (PMID 27101199, 2016). "The importance of mTOR was corroborated by the decreased tumor burden in both of these PACC mouse models when treated with rapamycin." (PMID 27165126, 2016). "The clinical impact of hyperactive mTOR depends on the tumor type as it has been revealed in two recent meta-analyses examining data from numerous previous studies." (PMID 27119232, 2016). "Collectively, our in vitro experiments clearly show that blockade of mTOR by MLN0128 inhibits MCC cell growth which partly accounts for the phenotype reduction of tumor." (PMID 26536665, 2016). "Various upstream proteins, such as ERK, mTOR and Wnt, are involved in the inactivation of GSK3β and tumor metastasis." (PMID 27806330, 2016). "Mechanism investigation indicated that ATR-1 exerts its anti-tumor effect also relies on the inhibition of PI3K/Akt/mTOR signaling pathway." (PMID 26931119, 2016). "The percentages of CD11b+ Ly6Chigh monocytic cells in the peripheral blood, spleens and tumor mass of Lyzs-mTOR KO mice were significantly lower than those in WT recipients (P < 0.001)." (PMID 26833095, 2016). "Our studies demonstrate that as a tumour suppressor, miR-3188 directly targets mTOR to stimulate its own expression and participates in FOXO1-mediated repression of cell growth, tumorigenesis and NPC chemotherapy resistance." (PMID 27095304, 2016). "Since mTOR is known to play a pivotal role in cell growth and proliferation, mTOR inhibition by everolimus exhibited significant anti-tumor effect as expected, both in the absence and presence of CDD866." (PMID 27462398, 2016). "A relevant study demonstrated an autocrine feed-forward loop in NSCLC cells in which tumor-derived VEGF stimulated VEGF production via VEGFR2-dependent activation of PI3K/ mTOR." (PMID 27806094, 2016). "Among numerous evaluations of the expression profiles of the PI3K/Akt/mTOR signaling components in human tissue samples, p70S6K upregulation and activation have been proven to be correlated with tumor malignancy, metastasis, and poor patient survival." (PMID 27174914, 2016). "We conclude that duration of drug treatment before irradiation plays a key role in the concomitant targeting of PI3K/mTOR and Hsp90 in tumor cells." (PMID 27224913, 2016). "In this study we identified a panel of deregulated miRNAs in PTC specimens compared to normal thyroid and among these we showed that miR-451a is underexpressed and displays tumor suppressor functions by targeting multiple elements of the AKT/mTOR pathway." (PMID 26871295, 2016).
tumor (continued). "The serine/threonine protein kinase mTOR is part of a protein complex called mTORC1, which has important roles in tumor cell growth and metabolism." (PMID 26878387, 2016). "Constitutive activation of mTOR is commonly found in tumour cells, but in quiescent normal cells mTOR activity and biosynthetic pathways are suppressed." (PMID 26985829, 2016). "Other than PI3K/AKT signaling network, previous reports also demonstrated an essential role of STAT3 and its regulation by PI3K/mTOR signaling in tumor progression." (PMID 27875549, 2016). "In conclusion, quercetin at 15μM in vitro and 15 mg/kg BW in vivo, inhibits Akt/mTOR signaling, induces cell cycle arrest, and inhibits BC cell and tumor growth, and appears to be the most active ingredient in the RQC formulation." (PMID 27285995, 2016). "In order to determine the molecular mechanisms underlying DEPTOR mediated tumor suppression, AKT/mTOR signaling pathway was tested by western blotting in our established cells lines." (PMID 26893358, 2016). "Percentage of tumor cells with positive staining for phosphorylation of S6R (Ser240/244) and phosphorylation of 4EBP1 (Thr37/46) were scored on the same TMAs used for p-mTOR." (PMID 27096957, 2016). "EGFR activation elicits its effects partially via PIK3CA/AKT/mTOR pathways, which promote tumor proliferation, invasion, and migration." (PMID 27554588, 2016). "Then we examined the effect of AZD3463 on the PI3K/AKT/mTOR signaling in the tumor tissues and found that AZD3463 efficiently blocked Akt and RPS6 phosphorylation and induced the cleavage of PARP, caspase 3, and LC3 A/BΙΙ in vivo." (PMID 26786851, 2016). "Our results provide further evidence showing that mTOR activation (by means of p-S6 expression) has a distinct impact on patient survival depending on the tumor localization." (PMID 27119232, 2016). "Markers indicating an activated PI3K/mTOR pathway were found to follow this pattern with highest expression in the periphery of the tumours." (PMID 27291893, 2016). "We here briefly review drug resistance against VEGF- and mTOR-targeted inhibitors and its role in directing tumor metabolism." (PMID 27418963, 2016). "Immunohistochemistry was used to assess GOLPH3 and mTOR (mammalian target of rapamycin) in tumor tissues." (PMID 27634904, 2016). "Widespread genetic alterations in the mTOR pathway members are common in OvCa patients and comparable aberrations lead to the development of histopathologically similar tumours in mouse models." (PMID 27036037, 2016). "Altogether, our results indicate that conditioning of T cells with MDSC induces survival pathways characterized by a blunted mTOR signaling, which prevents T cell differentiation and increases the anti-tumor efficacy of ACT." (PMID 27007050, 2016). "Collectively, our functional analyses showed that in PTC, miR-451a affects cell proliferation and migration and targets multiple elements of the AKT/mTOR pathway, thus appearing to play a role as tumor suppressor miRNA in this neoplasia." (PMID 26871295, 2016). "Recent studies showed that the inhibition of mTOR in T cells enhanced their survival and anti-tumor activity after ACT." (PMID 27007050, 2016). "One potential way forward is to develop ways of inhibiting those steps downstream of mTOR, especially mTORC1, that play critical roles in oncogenesis and tumor progression." (PMID 27635236, 2016). "As we have discussed here, PI3K/Akt/mTOR signal pathway after activation of EGFR is one of the most significant signal pathways in tumor cells." (PMID 26967052, 2016). "As known, mTOR, p70S6 kninase and S6 ribosomal protein constitute an important signaling axis involved in the regulation of tumor growth and metastasis." (PMID 27863387, 2016). "Many of the proteins that negatively regulate mTOR are tumor suppressors, such as PTEN, AMPK, and TSC1/2." (PMID 27034171, 2016).
tumor (continued). "Regardless, the virus-induced activation of AKT/mTOR signaling in vivo seems temporary and therefore its impact on tumor growth is probably quite limited." (PMID 27849011, 2016). "Patients with activated mTOR signaling in tumor cells are expected to benefit from treatment with mTOR inhibitors, such as everolimus, rapamycin and temsirolimus." (PMID 27096957, 2016). "Mitogen-activated cascades are also critical, where inhibition of mitogen-activated protein kinase (MAPK) and the phosphatidylinositide 3-kinase/Akt/mammalian target of rapamycin PI3K/Akt/mTOR pathways have been shown to inhibit tumour growth." (PMID 27443843, 2016). "Temsirolimus is an mTOR inhibitor that inhibits the phosphoinositide 3-kinase (PI3K)/Protein kinase B (AKT)/mTOR pathway, which is involved in protein synthesis, cellular proliferation, and tumor angiogenesis." (PMID 26933802, 2016). "Tumor development usually involves a hypoxic state sensed by the mTOR pathway leading to an activation of the hypoxia-inducible factor 1 alpha (HIF1A) to facilitate angiogenesis upon VEGFA induction." (PMID 27090655, 2016). "WYE-125132, WYE-354, P7170, and AZD8055 are examples of novel mTOR inhibitors that induced tumor shrinkage in preclinical RCC models." (PMID 27418963, 2016). "Activated EGFR recruits a variety of downstream signaling molecules, leading to the activation of major signaling pathways such as JAK2-STAT3, MAPK-ERK, and PI3k-Akt-mTOR, which play vital role in tumor growth, progression, and survival." (PMID 27649234, 2016). "Metformin has been reported to inhibit tumour progression of cancer cells by inhibiting mTOR via AMPK." (PMID 27213336, 2016). "We found that components of the mTOR signaling pathway were present in five (GBMs 6, 8, 10, 12 and 15) out of eight tumor lines." (PMID 27354287, 2016). "The poor immunosuppressive ability and the enhanced inflammatory function of CD11b+ Ly6Chigh M-MDSCs likely contribute to the accelerated alloskin and tumor graft rejection in mTOR KO recipients." (PMID 26833095, 2016). "TRIM44 overexpression promotes the EMT program and, thus, tumor invasion/metastasis in NSCLC cells via the mTOR signaling pathway." (PMID 27058415, 2016). "To identify the potential underlying mechanisms for this effect, we subjected xenograft tumor tissues to Western blot analyses against p-AMPK, p-mTOR and mesenchymal phenotype-associated proteins (i.e., slug, vimentin, N-cadherin, and ZEB1)." (PMID 27223262, 2016). "Conversely, by using focused inhibition of Akt1, there would be refined and enhanced anti-tumor effects through inhibition of Akt/mTOR signaling, tumor cell proliferation and survival and metastasis." (PMID 27533079, 2016). "We demonstrate that gene expression profiles derived from chemically-induced protein inhibition allows us to measure PI3K-Akt-mTOR pathway activity in patient tumor samples." (PMID 27589846, 2016). "Gene mutations and copy number alterations (CNAs) activate the AKT/mTOR pathway in many tumor types, and numerous studies demonstrate that mTOR kinase suppresses autophagy and apoptosis." (PMID 27027343, 2016). "So, identification of tumor types that respond to mTOR inhibitors remains a major issue for the application of mTOR inhibitors in therapy." (PMID 29083380, 2016). "We also found that the down-regulated expression of mTOR in the primary tumor tissues was comparable with that of the corresponding liver metastases." (PMID 26259252, 2015). "The next example, for the mTOR targeting agent temsirolimus, yielded a minimal EN model consisting of 67 genes and 108 tumor cells." (PMID 26132924, 2015). "Functional consequences of MEK and mTOR inhibition were assessed by evaluating for tumor cell proliferation and apoptosis in vivo." (PMID 26506415, 2015). "Increased mTOR activity can promote tumor growth and mTOR inhibitors are already used in the clinic." (PMID 25767478, 2015).